EGFR (epidermal growth factor receptor)
Diseases named in the same sentence as EGFR in open-access papers (continued):
Sharing a sentence is not in itself a finding about the gene and the disease.
glioma (continued). "An association has been demonstrated between EGFR amplification and increased invasiveness and between proliferation of glioma cells and resistance to radiotherapy." (PMID 40428422, 2025). "Mechanistically, the antineoplastic effect of SCU and its combination with lidocaine on glioma was partially associated with the repression of EGFR signaling." (PMID 39888904, 2025). "In this study, we found that EGFRvIII was the most common form of EGFR mutation, with an incidence rate of 22.13% in glioma patients and 33.3% in GBM patients." (PMID 40527884, 2025). "It is important to acknowledge that TGFA has previously been implicated in gliomas, largely through its role as a ligand of EGFR." (PMID 41267963, 2025). "Precision oncology in CNS cancers is made possible by the molecular pathways covered, including EGFR amplification, IDH1/2 mutations, and MGMT promoter methylation." (PMID 41311621, 2025). "This suggests panitumumab as a promising candidate for future clinical trials in glioma patients with EGFR mutations." (PMID 39877359, 2024). "Conversely, EGFR amplification is associated with poor prognosis in glioma, and was significantly reduced in CR-mut GBM, IDH-WT overall." (PMID 39553337, 2024). "HBEGF and TGFA serve as established ligands for EGFR, and their intricate interplay triggers a cascade of signaling pathways implicated in glioma development." (PMID 39722126, 2024). "Specific genomic alterations such as amplification and activating mutations in the EGFR have been identified as one of the causes of initiating glioma." (PMID 38515213, 2024). "It is worth noting that the frequency of IDH1 mutations was higher compared to EGFR-amp in Grade 2, 3, and 4 gliomas." (PMID 38893240, 2024). "In terms of KEGG pathway enrichment, hypermethylated genes showed a strong association with “EGFR tyrosine kinase inhibitor resistance” and “glioma”." (PMID 38575994, 2024). "The primary tumor-specific antigen in gliomas is a mutated form of EGFR, EGFRvIII, which is found in about 30% of malignant glioma cases." (PMID 38927583, 2024). "Unsurprisingly, these two are CpG sites and correspond to amino acid change of V774M and R222C in EGFR, which are canonical actionable driver mutations in glioma target therapy." (PMID 39688960, 2024). "BRAF has been reported to occur in various gliomas, and EGFR is one of the diagnostic indicators of grade 4 GBM of the WHO." (PMID 39771050, 2024). "Our results also showed that mitochondrial gene lost is associated with high hypoxia score in HG gliomas, accompanied by increased expression of EGFR and other proliferative markers." (PMID 39257581, 2024). "For example, glioma cells expressing EGFR variant III (EGFRvIII) secrete these in EVs that are internalised by EGFRvIII negative recipient cell in the tumor to activate MAPkinase and protein kinase B signaling pathways and promote tumor phenotype 37." (PMID 39431017, 2024). "In the replication dataset, the top SNP for astrocyte EGFR eQTL was identified as rs723527, a known glioma risk locus that is also situated at 7p11.2." (PMID 39722126, 2024). "The epidermal growth factor receptor (EGFR) gene is associated with seizure risk in glioma patients both preoperatively and postoperatively." (PMID 38641945, 2024). "In glioma, the most common cause of abnormal activation of the EGFR pathway is EGFR amplification and mutation." (PMID 39054543, 2024). "Both EGFR amplification and the occurrence of EGFRvIII mutations predict a poor survival prognosis in glioma patients." (PMID 39054543, 2024). "Among these, we focused specifically on EGFR, a tyrosine kinase receptor that is extensively associated with the occurrence and progression of gliomas." (PMID 39722126, 2024).
glioma (continued). "EGFR-mutant DMG should be distinguished from tectal glioma based on histomorphology, wild-type EGFR, and frequent KRAS BRAF mutations." (PMID 39440342, 2024). "For instance, glioma cells transfer oncogenic EGFR variant III (EGFRvIII) via EVs to other glioma cells lacking this receptor, promoting their morphological transformation and cell proliferation by activating the MAPK and AKT signaling pathway." (PMID 39611045, 2024). "Tumor tissue taken in these areas was rich in CD31, VEGFA and EGFR that were associated with poor prognosis in glioma patients." (PMID 37534312, 2023). "Studies of glioma showed that EGFR was associated with the degree of malignancy and angiogenesis of tumor." (PMID 37810780, 2023). "Multiple signaling cascades are dysregulated in glioma, including EGFR, the type III mutations, VEGFR and CDK, which are essential for the uncontrolled glioma growth and malignant progression 4-8." (PMID 36778118, 2023). "Fcγ-CR T lymphocytes, equipped with monoclonal antibodies, can be highly specific against surface antigens associated with gliomas, such as epidermal growth factor receptor (EGFR) and platelet-derived growth factor (PDGFA)." (PMID 38139688, 2023). "Other factors, such as EGFR overexpression or EGFRvIII mutations leading to the downregulation of miRNA-524, also have the ability to suppress miRNA activity in gliomas." (PMID 37626776, 2023). "Other variants, such as IDH2, BRAF, and PIK3A, had low-frequency and were mainly present in patients with other gliomas, while low-frequency EGFR variants were more common in GBM patients." (PMID 36959606, 2023). "Namely, the role of secondary mutations in epigenetically driven glioma has only been superficially defined, with an unclear role of key oncogenic driver genes such as EGFR, PTEN, RB1, NF1, TERT, and CDKN2A on modulating the tumor microenvironment." (PMID 37706202, 2023). "Similar to the interaction between CD44v and xCT, EGFR is associated with xCT and its stabilization on the plasma membrane to facilitate cystine uptake in glioma cells." (PMID 36961000, 2023). "The EGFR variant III (EGFRVIII), formed by the deletion of exons 2–7, is the most common EGFR variant in high-grade gliomas and results in a constitutively active kinase whose activity is independent of ligand binding." (PMID 37242454, 2023). "EGFR (a receptor tyrosine kinase) mutations are frequently seen in high-grade gliomas; therefore, its overexpression has prognostic importance in clinical diagnosis." (PMID 37821870, 2023). "Epidermal growth factor receptor (EGFR) is an oncogene implicated in glioma initiation, tumour growth and progression." (PMID 37265788, 2023). "The experiment on glioma cells (U87) showed that PEG-NGO-C225 caused a significant decrease in EGFR expression, prolonging the survival of U87 tumor-bearing mice for 50 days." (PMID 36874010, 2023). "Clinical trials of CAR T-cell therapy for gliomas have primarily focused on targeting TAAs such as IL-13 receptor alpha 2 (IL-13Rα2), EGFR variant III (EGFRvIII) and human EGFR 2 (HER2)." (PMID 37686020, 2023). "An EGFR signaling-related risk score was established, and a higher score was correlated with poorer prognosis and a more malignant phenotype in gliomas." (PMID 37759950, 2023). "Important examples of molecular alterations in adult-type gliomas include EGFR amplification, TERT promoter mutation, and +7/-10 chromosomal copy number alterations in high-grade astrocytic tumors with IDH wild type." (PMID 37626776, 2023). "Most of the glioma cells overexpress the epidermal growth factor receptor (EGFR) which leads to abnormal behaviors of the underlying molecular signaling pathway." (PMID 38010378, 2023).
glioma (continued). "Specifically, CIC wild-type tissue exhibits higher mutation rates of MAPK-associated genes across all glioma subtypes, including more valent EGFR mutation, amplification, EGFRvIII variant, and EGFR fusion." (PMID 37291277, 2023). "Both the PI3K/Akt/mTOR and Ras/BRAF/Mek/Erk protein kinase pathways are also downstream of receptors such as EGFR, one of the most significant signaling pathways clinically implicated in glioma." (PMID 37445633, 2023). "Molecular alterations in pHGG are commonly associated with histone H3 mutations, whereas IDH mutations, PTEN loss, and EGFR amplifications are commonly found in adult gliomas." (PMID 37124503, 2023). "Previous studies found that IDH, 1p/19q, and EGFR are recognized molecular markers associated with the survival and prognosis of gliomas." (PMID 36747161, 2023). "Previous studies have confirmed the association between common genetic variants of EGFR and the heritable risk of gliomas." (PMID 36347915, 2022). "Variants in EGFR lead to overexpression of the EGFR protein have been associated with many cancers, including gliomas." (PMID 36347915, 2022). "The first mutation in the EGFR gene was found in human gliomas, where amplification and overexpression of EGFR were frequent." (PMID 35455447, 2022). "In EGFR mutated gliomas, the hyperactivation of EGFR leads to epigenetic changes, which promote cancer progression, such as the upregulation of c-Myc and cyclin D1 (CCND1)." (PMID 35681635, 2022). "These truncated EGFR proteins have been seldom observed in NSCLC, so the overexpression or amplification of EGFR in NSCLC cannot be explained by these extracellular mutations observed in human gliomas." (PMID 35455447, 2022). "A further study found that the genetic risk for acquiring glioma was associated with EGFR in males, and to TERT instead in females, indicating biologically relevant sex differences in gliomagenesis." (PMID 35159938, 2022). "Dysregulation of the epidermal growth factor signaling pathway can be observed in approximately 80% of high-grade gliomas, resulting either from aberrant expression of EGFR or an EGFR variant (EGFRvIII)." (PMID 35330402, 2022). "In gliomas, MRI imaging data and radiometric analysis based on these data were also used to analyze the EGFR mutation status of tumors." (PMID 35663041, 2022). "High EGFR expression was associated with poor response to radiation or chemoradiotherapy, and specifically targeting EGFR and EGFR variant receptors is undergoing clinical evaluation in patients with glioma." (PMID 36045691, 2022). "This study is the first to show evidence that functional variants of EGFR, namely, rs2227983 (K521R) and rs1050171 (Q787Q), are associated with an increased risk of glioma in the Korean population." (PMID 36347915, 2022). "Statistical analyses of the association between EGFR SNPs and glioma risk were conducted using logistic regression." (PMID 36347915, 2022). "Survival analysis further suggested regulatory correlations: elevated expression of FAM18A-AS1 and miR-21 was associated with poor prognosis in low-grade glioma, and high expression of EGFR, WEE1, MAP2K3, JA1, and EPHA2 was associated with poor prognosis." (PMID 35296768, 2022). "Somatic aberrations in the EGFR, including amplification and activating point mutations, occur in ∼57% of grade IV gliomas but are relatively uncommon in LGGs." (PMID 35211690, 2022). "For instance, FGFR3-TACC3 fusion and TERT promoter mutation are more closely associated with adult-type glioma, H3 K27-altered mutation is associated with pediatric-type glioma and EGFR mutation to both." (PMID 35436952, 2022).
glioma (continued). "Next, we performed an integrated analysis of EGFR amplification and molecular glioma hallmarks: IDH1/2 mutations, TERT promoter mutations, MGMT promoter methylation, and LOH 1p/19q." (PMID 35453544, 2022). "According to a previous report, mutant epidermal growth factor receptor variant III (EGFR vIII) mutation and EGFR overexpression glioma cells impaired physiological adaptation to starvation and rendered cells sensitive to hypoxia-induced cell death." (PMID 35785200, 2022). "Further, resistance to BRAF inhibition was observed in V600E-mutated glioma cell lines with additional epidermal growth factor receptor (EGFR) amplification." (PMID 35158978, 2022). "EGFR mutation has been reported to be an independent predictor of the prognosis in all grades of gliomas." (PMID 36092895, 2022). "Many cancers, including glioma, are known to increase EGFR activity due to gene mutations, overexpression, or amplification.12,13." (PMID 36347915, 2022). "Thalamic gliomas—mainly bilateral at the onset, showing EGFR variants, EZHIP (ex CXorf67) overexpression, and loss of H3.3K27me3 in the absence of H3F3A variants—have recently been described." (PMID 35456430, 2022). "Epidermal growth factor receptor (EGFR) is overexpressed in gliomas and associated with rapid proliferation and invasion." (PMID 35874843, 2022). "Gliomas co-opt developmental pathways to maintain cell proliferation and migration, properties associated with EGFR activation." (PMID 36509746, 2022). "Glioma-associated EGFR mutant forms have constitutive kinase activity, which drives cellular proliferation and migration by persistently stimulating Ras signaling." (PMID 36003330, 2022). "The purpose of this study was to investigate the genetic association between SNPs in EGFR and the risk of glioma in a Korean population." (PMID 36347915, 2022). "The spectrum of EGFR variants in childhood brain tumours is significantly different compared to those reported in adult glioma." (PMID 36505819, 2022). "For lower-grade glioma, it was shown that mutated EGFR was present together with an upregulated immune response, indicating interactions with a prognostic value between the immune microenvironment and the molecular status." (PMID 34687436, 2022). "In previous GWASs, SNPs in epidermal growth factor receptor (EGFR) have been reported as risk loci for gliomas." (PMID 36347915, 2022). "c-Met is more associated with a stronger invasion of gliomas by inducing stronger EMT compared with EGFR and VEGFR." (PMID 36338770, 2022). "According to available data, EGFR amplifications and combined Chr7 gain/Chr10 loss were essentially present in NT-2 gliomas (89/188 samples, 47.3% and 129/188 samples, 68.6%, respectively)." (PMID 35455749, 2022). "The high ALKBH5-expressing glioma patients showed higher EGFR mutational rate compared to those with low ALKBH5 expression (24% vs. 15%)." (PMID 35444654, 2022). "The inclusion of more patients with IDH1/2 and ATRX mutations in the low-risk group and more patients with EGFR mutations in the high-risk group indicates that BM-gene-related risk scores can distinguish glioma patients with different prognoses." (PMID 36292695, 2022). "Due to the large number of EGFR variants (> 5500 variants), we only considered important coding variants and previous glioma variants." (PMID 36347915, 2022). "EGFR mutations are prevalent in multiple tumors and are often associated with adverse prognostic consequences in glioma patients." (PMID 36292695, 2022). "Stepwise and conditional analyses were performed on the two significant EGFR variants to verify the independent association between significant SNPs and glioma risk." (PMID 36347915, 2022).
glioma (continued). "In another study protein expression of EGFR+ EVs were illustrated as effective diagnostic and prognostic markers of glioma, wherein EGFR expression in serum EVs were able to accurately differentiate high-grade and low-grade glioma patients." (PMID 33968983, 2021). "ScRNA-seq was applied to study promotion of the immunosuppressive microenvironment through changes such as the increased expression of protein disulfide isomerase family A member 3 (PDIA3) associated with PTEN loss and EGFR amplification in gliomas." (PMID 34108022, 2021). "TERTp mutation was detected in 37 cases, and EGFR amplification was shown in 15 out of 37 TERTp mutant gliomas and in 4 of 19 TERTp-wild-type gliomas." (PMID 34257410, 2021). "EGFR is a receptor tyrosine kinase which is mutated or dysregulated in many cancers, especially glioma." (PMID 34843542, 2021). "They found the loss of PHD3 in glioma cells increased EGFR signaling, increased proliferation and reduced apoptosis relative to PHD3-expressing cells under low growth factor and starvation conditions." (PMID 33799686, 2021). "Many EGFR variants have been identified in gliomas, including amplification, overexpression, insertion-deletion (indel), point mutations, rearrangements, and other aberrations." (PMID 35601813, 2021). "Several alterations of the epidermal growth factor receptor (EGFR) are known for glial tumors: mutations, overexpression, and variant expression, which often lead to a ligand-independent, oncogenic function." (PMID 34771592, 2021). "Immunohistochemical techniques have shown prodigious results in the role of epidermal growth factor receptor variant III (EGFR vIII) in glioma and other cancers." (PMID 34582442, 2021). "EGFR has already proven to be a potential target to deal with the tumors like breast, lung, and glioma, etc. whereas the capability of its variant III as a drug target is yet to be discovered." (PMID 34582442, 2021). "The cytolytic activity-related PDGFA and EGFR genes have been found to be overexpressed in glioma, and a positive association between cytolytic activity and HLA expression has been observed; however, the underlying mechanisms are still being evaluated." (PMID 34660294, 2021). "In contrast, gliomas from older patients were more likely to be IDH-WT with EGFR mutations, chromosome 7 gain and 10 loss, CDKN2A deletion and worse prognosis." (PMID 33879792, 2021). "Epidermal growth factor receptor variant III (EGFRvIII), the most common EGFR gene specific mutation in glioma and GSCs." (PMID 34630121, 2021). "This shift is associated with downregulation of PDFGR and EGFR and is supportive of a role for glial determinants altering the cellular constituency and fate of glioma cells." (PMID 34012965, 2021). "Endocytosis and membrane trafficking play important roles in tumour cell migration and invasion and EGFR trafficking dysregulation has been associated with an invasive profile on glioma cells." (PMID 34831480, 2021). "Dual targeting of both wildtype EGFR and EGFRvIII has been shown to have more effective anti-tumor activity in intracranial murine glioma models than single targeting of either variant alone." (PMID 34926242, 2021). "Proneural GBs have shown to be enriched for activating mutations in the PDGFR-α gene and also comprise IDH mutated gliomas, whereas classical GB is enriched for EGFR amplification." (PMID 34209513, 2021). "Conversely, later-onset gliomas were associated with the IDHwt subtype paired with EGFR or MDM4 amplification, as well as with CDKN2A, CDKN2B, or PTEN deletion (FDR <0.015)." (PMID 34788626, 2021). "Significantly higher EGFR protein overexpression and gene amplification are more characteristic of high-grade gliomas compared to low-grade gliomas, and are implicated in tumor cell migration and aggressiveness." (PMID 33707521, 2021).